SYNGR1 (synaptogyrin 1)
Description:
May play a role in regulated exocytosis. Modulates the localization of synaptophysin/SYP into synaptic-like microvesicles and may therefore play a role in synaptic-like microvesicle formation and/or maturation (By similarity). Involved in the regulation of short-term and long-term synaptic plasticity (By similarity).
Tractability: Antibody: its Gene Ontology location is reachable by antibodies, with high confidence; UniProt predicts a signal peptide or a membrane-spanning region. PROTAC: ubiquitination databases record sites on it; its protein half-life has been measured.
Gene: Protein-coding gene on chromosome 22 (39,349,909 to 39,385,588, forward strand). Ensembl gene ENSG00000100321.
Subcellular location: Cytoplasmic vesicle, secretory vesicle, synaptic vesicle membrane; Melanosome
Subcellular location (Human Protein Atlas): Cytosol
Pathways (Reactome):
Immune System: Neutrophil degranulation
Gene Ontology:
Molecular function: protein binding
Biological process: regulated exocytosis; regulation of long-term neuronal synaptic plasticity; regulation of short-term neuronal synaptic plasticity; synaptic vesicle membrane organization; modulation of chemical synaptic transmission
Cellular component: cytosol; melanosome; azurophil granule membrane; neuromuscular junction; plasma membrane; synaptic vesicle membrane; membrane; Schaffer collateral - CA1 synapse; synaptic vesicle
Genetic constraint (gnomAD): Loss-of-function variants: 14 observed, 24.29 expected, observed/expected ratio (o/e) 0.58, 90% interval 0.38 to 0.9. The upper end of that interval is the gene's LOEUF score, 0.9, which puts it in group 3 of 6, group 1 being the genes least tolerant of losing a copy. Missense variants: 319 observed, 325.92 expected, observed/expected ratio (o/e) 0.98, 90% interval 0.89 to 1.07. Synonymous variants: 141 observed, 146.73 expected, observed/expected ratio (o/e) 0.96, 90% interval 0.84 to 1.11.
Homologues: Orthologues: chimpanzee SYNGR1 (99% identical), pig SYNGR1 (97% identical), mouse Syngr1 (94% identical), rat Syngr1 (94% identical), macaque SYNGR1 (91% identical), guinea pig SYNGR1 (91% identical), dog SYNGR1 (73% identical), zebrafish syngr1a (63% identical), zebrafish syngr1b (43% identical), Drosophila melanogaster Syngr (39% identical). Paralogues in human: SYNGR3 (50% identical), SYNGR2 (48% identical), SYNGR4 (31% identical).
Diseases named in the same sentence as SYNGR1 in open-access papers:
SYNGR1 is named in the same sentence as 23 diseases in open-access papers, as found by Europe PMC text mining. Sharing a sentence is not in itself a finding about the gene and the disease. The quoted sentences say what the papers report.
schizophrenia (4 papers, 2012 to 2023). A major psychotic disorder characterized by abnormalities in the perception or expression of reality. "A number of mutations, insertions and deletions of the gene encoding synaptogyrin 1 were identified in schizophrenia patients suggesting that aberrant synaptogyrin 1 function may be involved in the pathogenesis of schizophrenia." (PMID 22675529, 2012).
rheumatoid arthritis (3 papers, 2012 to 2023). A chronic, systemic autoimmune disorder characterized by inflammation in the synovial membranes and articular surfaces. "For instance, the A allele of rs909685 (T/A), located in the intron of the synaptogyrin-1 (SYNGR1) gene, has been shown to increase the susceptibility to rheumatoid arthritis (RA) for individuals of European, Asian, and African ancestries." (PMID 37425716, 2023).
bladder cancer (2 papers, 2016 to 2024). "SYNGR1 has differential expression between bladder cancer with different risk of recurrence." (PMID 27494850, 2016). "The expression of SYNGR1 was downregulated in bladder cancer." (PMID 38741142, 2024).
triple-negative breast carcinoma (2 papers, 2017 to 2024). An invasive breast carcinoma which is negative for expression of estrogen receptor (ER), progesterone receptor (PR), and human epidermal growth factor receptor 2 (HER2). "The shortening of 3′ UTRs of SYNGR1 was associated with poorer prognosis in triple-negative breast cancer." (PMID 29312619, 2017). "Notably, the TRs of several genes, including SYNGR1, GTF2IRD2, and FAM120C, exhibited increased levels in the tumor samples of triple-negative breast cancer patients, whereas genes such as TVP23C, ICAM3, and RIMKLB displayed decreased TRs in triple-negative breast cancer tumor samples." (PMID 39349823, 2024).
ovarian carcinoma (1 paper, 2018). A malignant neoplasm originating from the surface ovarian epithelium. "Our finding suggested that SYNGR1 and higher level of SYNGRI expression may plausibly increase ovarian cancer risk." (PMID 30557369, 2018).
Stroke (1 paper, 2025). Sudden impairment of blood flow to a part of the brain due to occlusion or rupture of an artery to the brain. "We identified 179 significant SNPs and five common risk genes for RA and stroke (IRF5, RNASET2, ZNF438, UBE2LS, and SYNGR1)." (PMID 39953635, 2025).
SYNGR1 also shares sentences with these, for which no sentence is quoted: tumor (2 papers); Alzheimer disease (1); berylliosis (1); bipolar disorder (1); Hypertension (1); hypopharyngeal cancer (1); lung adenocarcinoma (1); lung carcinoma (1); mammary tumour (1); myocardial infarct (1); narcolepsy (1); nasopharyngeal carcinoma (1); neurodegenerative disease (1); pregnancy disorder (1); prion disease (1); psychiatric diseases (1); type 1 diabetes (1).